SOAT1 (sterol O-acyltransferase 1)
Diseases named in the same sentence as SOAT1 in open-access papers (continued):
Sharing a sentence is not in itself a finding about the gene and the disease.
tumor (continued). "Moreover, our findings shed light on the association between SOAT1 expression and TMB, MSI, or infiltrated immune cells, although its effect on tumor immunity varied." (PMID 37304239, 2023). "Moreover, after treatment with two SOAT1-targeting compounds, tumor growth in mice was not only inhibited, but also tumor size was subsided after 2 weeks of dosing." (PMID 35941608, 2022). "We identified nilotinib as SOAT1-targeting compounds, and we further demonstrated via various experiments that these compounds have a high affinity with SOAT1 protein and significantly inhibit tumor activity in vitro and in vivo." (PMID 35941608, 2022). "Furthermore, avasimibe, an inhibitor of SOAT1, was reported to markedly reduce the size of tumours that had high levels of SOAT1 expression." (PMID 36010562, 2022). "Finally, we repositioned mitotane, an FDA-approved SOAT1 inhibitor, to treat ccRCC and showed that it decreased tumor cell viability and inhibited tumor cell growth based on in vitro experiments." (PMID 34258555, 2021). "Previous research demonstrated that SOAT1 promotes lipid metabolism and tumor growth." (PMID 34790132, 2021). "SOAT1 protein expression in HCC cell lines and inhibition of patient-derived tumor xenograft models demonstrated that SOAT1 suppression may be an effective HCC treatment." (PMID 34039309, 2021). "As was done for SOAT1, an experimental setup that could elucidate the mechanism behind suppressed tumor growth is desirable, to test the hypotheses proposed in this paper." (PMID 32362913, 2020). "Heterogeneity of SOAT1 expression within a single tumor may be underestimated by using tissue microarray." (PMID 31963898, 2020). "We had access to formalin-fixed paraffin-embedded tissue from the tumor recurrence in patient 2 and used it for carrying out immunohistochemistry for SOAT1, which demonstrated predominantly high and moderate expression, detected in 60% and 30% of the cells, respectively." (PMID 29330226, 2018). "In addition, SOAT1 knockdown also inhibited tumor growth and metastasis in vivo." (PMID 40135589, 2025). "The tumor-promoting impact of SOAT1 in OSCC may be attributed to its effect on lipid metabolism." (PMID 38993570, 2024). "After adjustment for age, preoperative PSA, tumor stage, Gleason score, resection status, lymph node involvement and year of surgery, high SOAT1 but not SOAT2 expression was associated with shorter BCR free survival with a hazard ratio of 2.40 (95% CI 1.57–3.68, p < 0.001)." (PMID 34326474, 2022). "Furthermore, SOAT1 expression was elevated as the tumor grade increased." (PMID 35646697, 2022). "Thus, SOAT1-targeting compounds systematically restored the cholesterol metabolism in tumor cells." (PMID 35941608, 2022). "Therefore, SOAT1 inhibition may mediate dual anti-tumor effects in cancer treatment in terms of tumor inhibition and immunity enhancement, and is likely to have value in combination with immunotherapy." (PMID 34820325, 2021). "Next, we further examined whether SOAT1 has an effect on tumor-induced lymphangiogenesis." (PMID 34790132, 2021). "A previous study demonstrated that simultaneously targeting sterol O-acyltransferase 1 and CPT1A effectively suppressed tumor growth both in vitro and in vivo." (PMID 39708716, 2025). "SOAT1 inhibitors reduce these effects on HBV/HCC-specific tumor-infiltrating cells, potentially reducing tumor progression." (PMID 40869156, 2025). "High levels of the esterification enzyme sterol O-acyltransferase 1 (SOAT1) in certain HBV-related HCCs disrupts cholesterol balance, which, in turn, promotes tumor cell migration and proliferation." (PMID 40869156, 2025). "Mitotane, a DDT derivative with adrenal toxicity, inhibits Sterol O-Acyltransferase 1 (SOAT1) in ACC cells, disrupting cholesterol balance and enhancing oxidative stress sensitivity to suppress tumor growth." (PMID 40145087, 2025).
tumor (continued). "Previous study indicated that SOAT1 exhibits high expression in the S-III subtype of HCC, and knocked down SOAT1 inhibit tumor development." (PMID 38724499, 2024). "Through targeted interference with SOAT1 expression levels in OSCC cells, we found that SOAT1 promotes OSCC progression by increasing the proliferation, tumor sphere formation, migration, and invasive ability of OSCC cells." (PMID 38993570, 2024). "Impairment of cholesterol esterification through inhibition of sterol O-acyltransferase 1 (SOAT1) has also led to inhibition of SREBP-1 regulated fatty acid synthesis, impacting tumor growth in GB." (PMID 37298093, 2023). "Sterol O-acyltransferase 1 (SOAT1) responds to the mevalonate pathway to acquire cholesterol, which has been found to participate in all processes in tumour progression in an organoid model with differential regulation of cholesterol homeostasis." (PMID 36835437, 2023). "SOAT1-targeting compounds increase the CD8+ T cell ratio to total immune cells, and nilotinib inhibits tumor activity in vitro and in vivo." (PMID 37958351, 2023). "Multi-omics analysis and flow cytometry analysis indicated that SOAT1-targeting compounds reprogrammed the cholesterol metabolism in tumors and enhanced CD8+ T cells and neutrophils to suppress tumor growth." (PMID 35941608, 2022). "Based on metabolic modeling analysis, we identified four target genes, namely SOAT1, CRLS1, ACACB, and GPD2, whose inhibition can block the growth of ccRCC tumor cells with relatively low toxicity to normal tissue cells." (PMID 34258555, 2021). "We measured the SOAT1 protein expression by immunohistochemistry (IHC) in HCC liver tissue samples and paired non-tumor tissue samples from 42 patients." (PMID 34039309, 2021). "We compared characteristics of HCC patients (including LDL, HDL, TC, TG, tumor size, alpha-fetoprotein level (AFP), HBV status and pathological stage) between different SOAT1 genotypes and haplotypes." (PMID 34039309, 2021). "Yang and others proposed to use avasimibe, an inhibitor of the cholesterol esterification enzyme ACAT1/SOAT1, for therapy to improve CD8+ T cell mediated control of tumor growth." (PMID 31681760, 2019). "Furthermore, the sterol O-acyltransferase 1 (SOAT1) inhibitor Avasimibe disrupts lipid metabolism by reducing cholesterol ester synthesis, impairing lymphangiogenesis, and inhibiting tumor proliferation through downregulation of SREBP1/2 and VEGF-C." (PMID 41171531, 2026). "Patients with S-III subtype was associated with the lowest survival rate and the greatest risk of a poor prognosis after surgery, expressed high levels of SOAT1 protein in the tumour tissues compare to adjacent non-tumour liver tissues." (PMID 40687983, 2025). "A significantly higher SOAT1 mRNA levels in tumor tissues compared to adjacent noncancerous tissues were detected (p = 0.0085)." (PMID 40135589, 2025). "Immunoperoxidase single staining of GBM samples suggested SOAT1 to be more pronounced in microglia and macrophages rather than in tumor cells." (PMID 35409086, 2022). "Our immunohistochemistry results also found higher expression of SOAT1 in tumor tissue compared to paired non-tumor tissue." (PMID 34039309, 2021). "Further reports demonstrated that targeting SOAT1 could inhibit SREBP1-mediated fatty acid metabolism by increasing intracellular free cholesterol level, consequently inhibiting tumor growth." (PMID 33637695, 2021). "The result showed the expressions of SOAT1 and CPT1A were mildly decreased under a ND condition, but dramatically increased under HFD condition in HCC tissues compared with the adjacent non-tumor tissues." (PMID 34052835, 2021). "And the copy number variation of SOAT1 was elevated in tumor tissues compared with non-tumor tissues, while SOAT2 had no significance using the Oncomine database." (PMID 34052835, 2021). "We further conducted immunohistochemistry to compare SOAT1 protein expression levels in 42 paired tumor and adjacent non-tumor tissues." (PMID 34039309, 2021).
tumor (continued). "Furthermore, we assessed SOAT1 expression levels in fresh tumor samples and matched adjacent noncancerous samples (n = 19) by qRT‐PCR." (PMID 40135589, 2025). "Using TCGA data, SOAT1 expression levels were compared between tumor and paired normal tissues." (PMID 37304239, 2023). "Furthermore, suppression of SOAT1 inhibits the proliferation and migration of HCC cells and the treatment with the SOAT1 inhibitor avasimibe reduced the size of tumors in patient-derived tumour xenograft mouse models." (PMID 36144184, 2022). "However, as recently published in a larger ENSAT cohort, SOAT1 is not predictive of response to mitotane, neither other candidates such as RRM1were found to correlate to tumor response." (PMID 35565353, 2022). "In addition, inhibitors of Acyl Coenzyme A: Cholesterol Acyltransferases 1 (ACAT1), which also known as sterol O-acyltransferase 1 (SOAT1), could suppress tumor growth by downregulating cholesterol esterification (CE) in leukemia and triple-negative breast cancer." (PMID 37488496, 2023). "However, the biological function of SOAT1 in regulating tumor progression has not been elucidated." (PMID 37304239, 2023). "An unequivocal expression of SOAT1 in tumor cells could not be definitely established." (PMID 35409086, 2022). "When SOAT1 is inhibited, the cholesterol accumulation in the ER prevents SBREP1 to relocate to the Golgi, hence lipogenesis is not activated, and tumor growth is suppressed." (PMID 32362913, 2020).
infection (436 papers, 2004 to 2026). The state of being infected such as from the introduction of a foreign agent such as serum, vaccine, antigenic substance or organism. "We found that the enzymes cholesteryl ester hydrolase (Lipa) and sterol O-acyltransferase (Soat1), which regulate ChE metabolism, were upregulated after infection." (PMID 40463366, 2025). "Adding up to our previous findings, the data suggest SOAT1 as important host factor for ZIKV replication in more complex infection models and that targeting SOAT1 is an interesting approach for anti-flaviviral therapy." (PMID 39237833, 2024). "Soat1 expression increases eight-fold after infection with T. congolense in A/J, BALB/c and C57BL/6, and expression was up to four-fold higher in C57BL/6." (PMID 21085469, 2010). "The data indicated that in microglia, Acat1/Soat1 is significantly elevated in many neurodegenerative diseases, including several AD mouse models (in both AβPP and tau models), acute inflammation/infection mouse models, and a mouse model for aging (22 months of age)." (PMID 36982689, 2023). "Soat1 is clearly responding to infection and the probably damaging SNP could affect its function and may be contributing to the difference in expression." (PMID 21085469, 2010). "To understand their respective roles in SARS-CoV-2 infection we transfected siRNAs either individually or in combination to knockdown (KD) SOAT1 and SOAT2 expression in VeroE6-TMPRSS2 or Calu-3 cells prior to infection." (PMID 37134108, 2023).
bacterial infection (37 papers, 2010 to 2025). "Release of the pro-inflammatory LPS upon bacterial infection of the wounds may induce the expression of Dnmt1, which in turn upregulates the expression of CD36 and downregulates the expression of SOAT1 and ABCA1, probably by a DNA-methylation-based mechanism." (PMID 37291182, 2023).
neurodegenerative disease (30 papers, 2014 to 2025). A disorder of the central nervous system characterized by gradual and progressive loss of neural tissue and neurologic function. "Microglial Acat1/Soat1 expression is elevated in many neurodegenerative diseases and in acute neuroinflammation." (PMID 36982689, 2023). "Additionally, in a mouse model, genetic inactivation of ACAT1/SOAT1 was recently shown to benefit a rare pediatric neurodegenerative disease, Niemann-Pick type C1 (NPC1)." (PMID 36982602, 2023).
cardiovascular diseases (22 papers, 2016 to 2026). "However, few researches have been conducted regarding the relationship between SOAT1 gene and cardiovascular diseases." (PMID 31684966, 2019). "However research in models of Alzheimer’s and cardiovascular disease has shown that excessive CE formation leads to the activation of myeloid cells and subsequently to cellular damage and that this can be blocked by inhibiting ACAT1/SOAT1 activity." (PMID 40603564, 2025).
metabolic disease (21 papers, 2017 to 2025). A congenital disorder (due to inherited enzyme abnormality) or acquired (due to failure of a metabolically important organ) disorder resulting from an abnormal metabolic process. "SCARB1 and SOAT1, despite evidence from metabolic disease models indicating that modulation of transcytosis or cholesterol esterification can alter intracellular lipid handling, currently lack any marketed therapeutics." (PMID 41446579, 2025). "Second, the selective depletion of polyunsaturated CE (22:2) species despite ACAT1/SOAT1 upregulation suggests a membrane quality control mechanism that may be compromised in metabolic diseases." (PMID 40806239, 2025).
heart disease (8 papers, 2020 to 2025). "A study reported that the methylation level SOAT1 is lower in patients with heart disease than normal." (PMID 35354120, 2022).
colorectal (6 papers, 2015 to 2023). "Next, we found a direct binding of β-catenin to SOAT1 promoter to activate transcriptional expression of SOAT1, which further induced cholesterol esterification and colorectal tumorigenesis." (PMID 34914638, 2022). "Because the ceramide/TLR4/β-catenin axis regulated SOAT1 expression in CRC, the role of SOAT1 in ceramide-mediated colorectal tumorigenesis was investigated by us." (PMID 34914638, 2022).
SOAT1 also shares sentences with these, for which no sentence is quoted: viral infection (279 papers); COVID-19 (163); rheumatoid arthritis (134); autoimmune disease (123); myeloproliferative neoplasm (109); inflammatory bowel disease (100); Sepsis (72); lymphoma (68); asthma (67); immune deficiency (65); Insulin resistance (61); immunodeficiency (58); systemic lupus erythematosus (58); bladder cancer (56); primary immunodeficiency (53); colitis (42); acute myeloid leukemia (39); myelofibrosis (39); Autoimmunity (38); type 2 diabetes mellitus (36); liver fibrosis (34); non-small cell lung carcinoma (33); hematological malignancies (32); multiple myeloma (32); vitiligo (32); endometrial cancer (31); atopic dermatitis (30); autoimmune thyroid disease (28); sarcoidosis (28); cardiac hypertrophy (27).
A further 627 diseases each share a sentence with SOAT1 in 27 papers or fewer.